FOLR1 (folate receptor alpha)
Diseases named in the same sentence as FOLR1 in open-access papers (continued):
Sharing a sentence is not in itself a finding about the gene and the disease.
ovarian endometriosis (1 paper, 2023). A non-neoplastic disorder characterized by the growth of endometrial tissue in the ovaries. "FOLR1 was highly expressed in the epithelia of fallopian tube and ovarian endometriosis, with paired endometrial samples showing a significantly lower level of expression." (PMID 36936232, 2023). "The folate receptor alpha gene FOLR1 identified through a differential gene array analysis is highly expressed in ovarian endometriosis and the fallopian tube epithelial cells." (PMID 36936232, 2023). "The expression of folate receptor alpha at both mRNA and protein levels in the tissues (fallopian tube or ovarian endometriosis vs. the endometrium) were significantly different (p < 0.001)." (PMID 36936232, 2023). "Real-time PCR was used to examine the level of FOLR1 expression in 15 paired fresh tissue samples (total of 45 samples, including 15 each of the fallopian tube, endometrium, and ovarian endometriosis specimens)." (PMID 36936232, 2023). "Similarly, the FOLR1 gene was highly expressed in the samples of ovarian endometriosis compared with the paired endometrium, with fold increment ranging from 3 to 20 (average fold change = 11.18, p < 0.001)." (PMID 36936232, 2023). "Since FOLR1 and its protein product FRA were highly differentially expressed in the tube and the eutopic endometrium, we assessed the tubal and endometrial samples with the FRA antibody on 50 patients with ovarian endometriosis (32 paired and 18 non-paired)." (PMID 36936232, 2023).
periodontal disease (1 paper, 2019). "On the other hand, GCF FOLR1 level does not totally reflect the degree of clinical parameters in patients with periodontal disease." (PMID 31604439, 2019). "Our preliminary data suggest that FOLR1 is not useful in monitoring the periodontal disease." (PMID 31604439, 2019).
prostate tumors (1 paper, 2024). "Analysis of the tumor/kidney ratio further supported the limited accumulation of folate–NIR in prostate tumors as compared to Hela tumors that highly express FOLR1." (PMID 38396800, 2024).
salivary gland carcinoma (1 paper, 2026). A carcinoma that arises from the major or minor salivary glands. "This retrospective study evaluated the expression of three immunologically relevant biomarkers-PRAME, FOLR1, and CLDN18.2-as potential therapeutic targets in salivary gland carcinomas." (PMID 41968569, 2026).
serous ovarian malignant tumors (1 paper, 2024). "Folate receptor alpha (FRa) is expressed in over 80% of serous ovarian malignant tumors and exhibits no response to chemotherapy." (PMID 39035742, 2024).
spina bifida (1 paper, 2018). A congenital neural tube defect in which vertebrae are not fully formed. "FOLR1 gene variants do not seem to be important in human anencephaly nor in spina bifida, although FOLR2 and FOLR3 may have a small role." (PMID 30134561, 2018). "It appears that, whereas most of the non-mitochondrial folate-pathway mutants previously reported do not have NTDs (the exception being Folr1), almost all of the mitochondrial folate-pathway mutants reported to date have exencephaly (with occasional craniorachischisis); none have spina bifida." (PMID 30134561, 2018).
uterine cancer (1 paper, 2025). Primary or metastatic malignant neoplasm involving the uterine corpus and/or the cervix. "The FOLR1 expression level is similar and follows the same pattern as in ovarian and uterine cancers, according to the GEPIA database." (PMID 39996761, 2025).
tumor (278 papers, 1993 to 2026). "In our system, tumor-specific scFv-Zip2 fusion proteins are used to target cancer-associated antigens (FOLR1, TROP2, and TF)." (PMID 41585490, 2026). "We report a population of high FOLR1-expressing tumor-associated macrophages (CD163 + FOLR1 + ), suggesting potential on-target, off-tumor immune editing by MIRV." (PMID 41888141, 2026). "FcγRIIIa was spatially associated with folate receptor alpha–positive (FRα+) tumor areas at baseline and in residual tumors following neoadjuvant chemotherapy." (PMID 41128663, 2025). "It depicts the mechanism by which CAR-T cells recognize and bind to specific tumor-associated antigens, including folate receptor alpha (FRα), mucin-1 (MUC1), and epithelial cell adhesion molecule (EpCAM)." (PMID 40281554, 2025). "First, we focused on evaluating FOLR1 gene expression in tumor tissue, GCTs, and their cisplatin-resistant variants." (PMID 39996761, 2025). "It is worth noting that anti-FOLR1 CAR candidate C induced a temporary weight loss correlating with delayed tumor elimination and higher IFN-γ and GM-CSF secretion." (PMID 38254822, 2024). "This temporary weight loss was confirmed in tumor-free mice after the injection of anti-FOLR1 CAR candidate C, indicating an off-target in vivo reactivity." (PMID 38254822, 2024). "These chips successfully simulated the off-tumor toxicity associated with T cell-engaging bispecific (TCB) antibodies targeting FOLR1 and CEA." (PMID 38711620, 2024). "CAR T cell therapies that target tumor-associated antigens, such as mesothelin and folate receptor alpha, have shown encouraging outcomes in early-phase clinical trials." (PMID 38075052, 2023). "Regardless of anti-FOLR antibody seropositive status, IL-17+BAFF+CpG combined with a monovalent tumour-associated antigen (folate receptor alpha [FOLR]) led to secreted antibodies recognizing the antigen and the antigen-expressing IGROV1 cancer cells." (PMID 35020866, 2022). "FOLR1 expression in the alveolar epithelium of cynomolgus and humans underlies on-target off-tumor toxicities of FOLR1-TCB and can be recreated in a human alveolus lung-chip." (PMID 34378534, 2021). "In previous studies, many alterations including the up-regulation of FUT8 39, increased core-fucosylation 40, excessive demands of folate, and the abnormal abundance of FOLR1 36-38 have been associated with tumor occurrence and development." (PMID 34093861, 2021). "Folate receptor alpha (FRα) has been associated with prognosis in several cancers and has served as a target of novel anti-tumor therapies." (PMID 28430580, 2017). "Despite being an essential vitamin, folate has been implicated to enhance tumor growth, as evidenced by reports on overexpression of folate receptor alpha (FRα) in carcinomas." (PMID 23144806, 2012). "We found that folate receptor 1 (FOLR1), a known secretory protein, was upregulated in tumor tissues and positively associated with 3 major stem/progenitor markers, KRT19, EPCAM, and PROM1, and a poor prognosis for HCC patients in both the discovery and validation cohorts." (PMID 40038575, 2025). "This restriction is lost in the setting of malignant transformation as FOLR1 becomes overexpressed in various solid tumors such as lung, breast, ovarian, and gastric cancers and is associated with more aggressive tumor behavior and poor response to chemoradiation." (PMID 40919994, 2025). "Folate receptor alpha (FRalpha) is a membrane transport protein with high affinity for folic acid; FRalpha levels are higher in specific malignant tumors of epithelial origin compared to normal tissues with a positive association to tumor stage and grade." (PMID 30282914, 2018). "The findings may provide the attractive diagnostic significance, including the value of tumor Folr1 as a molecular label in MB histopathology and the use of serum Folr1 as an indicator for pathogenic evaluation." (PMID 28416738, 2017).
tumor (continued). "Recent studies have demonstrated that folate receptor-alpha (FRα) may represent an ideal tumor-associated marker for immunotherapy for TNBC." (PMID 27439908, 2016). "Studies involving tumor-targeted probes against folate receptor alpha, α3-integrin, mesothelin, and CA125 were included, with emphasis on probe design, delivery, imaging performance, safety, and clinical relevance." (PMID 42198268, 2026). "The biological function of FOLR1 was validated by qRT-PCR, Western blotting, assessment in clinical specimens, and a subcutaneous xenograft tumor model in mice." (PMID 42122127, 2026). "By reducing the affinity of the BTN3A agonist and leveraging the increased avidity of the tetravalent, bispecific antibody, activation of BTN3A is restricted to FOLR1-positive tumors, thereby avoiding off-target activation of non-tumor cells." (PMID 40755782, 2025). "MOv18 IgE is the first‐in‐class anti‐cancer IgE, recognising the human TAA, folate receptor alpha (FRα), a glycosylphosphatidylinositol‐anchored membrane folate receptor that supports tumour growth." (PMID 40045925, 2025). "Here, we introduce the Evobody, a bispecific antibody that selectively activates BTN3A on FOLR1-positive tumor cells, thereby mimicking a localized bacterial infection and triggering a BTN3A-dependent immune response." (PMID 40755782, 2025). "The study elegantly demonstrated that targeting folate receptor-1 (FOLR1) can greatly improve the permeability of PROTACs in tumor cells, while also reducing their potential toxicity." (PMID 40143076, 2025). "Our single-cell analysis indicates that the majority of FOLR1 expression is localized in epithelial cancer cells compared with other stromal components in tumor samples from patients with HGSC." (PMID 40029935, 2025). "FOLR1 expression clinical cut-off is ≥75% viable tumor cells (TC) with membrane staining at moderate (2+) and/or strong (3+) intensity levels." (PMID 40508029, 2025). "Accurate quantification of FOLR1 expression in tumor cells is important for predicting the efficacy of FOLR1-targeting therapies." (PMID 40029935, 2025). "Having validated FOLR1 surface expression in U-2 OS, we evaluated the antitumor activity of FH FOLR1-CART by co-culturing tumor cells with CD8+ FH FOLR1-CART or NT T cells at various E:T ratios ranging from 10:1 to 1:1." (PMID 40919994, 2025). "We found that FOLR1 is expressed in TGCTs, with significantly higher levels in the tumor samples than in normal testes tissue by searching in publicly available research databases." (PMID 39996761, 2025). "The consistent findings from 2 independent cohorts indicated that FOLR1 was a tumor-derived prognostic marker for HCC." (PMID 40038575, 2025). "To this end, we measured the serum FOLR1 levels and tumor FOLR1 expression levels in 32 HCC patients who underwent surgical resection." (PMID 40038575, 2025). "Studies have shown that targeting FOLR1 or MSLN individually results in a 48-76% likelihood of near-complete tumor elimination, while simultaneous targeting of both proteins increases tumor cell killing to 88% in ovarian cancer." (PMID 40092990, 2025). "This study is the first to show the potential utility of both tumor-derived and circulating FOLR1 as a prognostic biomarker for HCC." (PMID 40038575, 2025). "Another example is Prot-FOLR1-TCB, a protease-activated anti-folate receptor 1 TCB, equipped with an anti-idiotypic anti-CD3 mask linked to the anti-CD3 Fab via a tumor protease-cleavable linker." (PMID 39911391, 2025). "This approval was accompanied by the VENTANA FOLR1 (FOLR-2.1) RxDx Assay, an immunohistochemical test used to identify FRα-positive tumors through moderate-to-strong membrane staining in at least 75% of tumor cells." (PMID 41301065, 2025). "The FOLR1-2.1 test comes with the PS2+ scoring system, which combines the proportion of FRα-expressing tumor cells with a four-level staining intensity scale (0 to 3+)." (PMID 41466165, 2025).
tumor (continued). "The folate receptors (FRs), especially FRα encoded by the FOLR1 gene, are predominantly expressed on tumor cell surfaces and minimally on normal cells." (PMID 40444179, 2025). "In this case, the Fab itself is non-reactive; however, when conjugated with folate, it binds to the folate receptor 1/alpha (FOLR1/FRα) which can be upregulated on tumour cells." (PMID 41465327, 2025). "Immunohistochemistry (IHC) is the gold standard for the qualitative assessment of FOLR1 (FRα) in tumor tissues/lesions." (PMID 40050918, 2025). "Initially, FOLR1 was identified as a surface target for OvCa with high expression levels on tumor cells, homogenous expression within individual tumors, and common expression across multiple patients." (PMID 38254822, 2024). "OV-90 wt xenografts treated with CAR T cells contained less FOLR1-expressing tumor cells whereas Mock treated and untreated tumors retained FOLR1 expression." (PMID 38254822, 2024). "We screened a naïve, human B cell receptor library to generate fully human scFv sequences specific for human and murine FOLR1, to be able to anticipate potential off-tumor reactivity in mouse studies." (PMID 39594628, 2024). "Following tumor establishment, anti-FOLR1 CAR T cells were intravenously injected at a single dose (1 × 107 CAR T cells, 85% transduction efficacy), and mice were monitored over a period of 21 d, including weekly blood withdrawals." (PMID 38254822, 2024). "Within the tumors, which were left post T cell infusion, more effector and less memory T cells were detected as expected for anti-FOLR1 CAR T cells in an FOLR1-expressing tumor." (PMID 38254822, 2024). "It has a bivalent binding arm for FOLR1, which allows it to selectively target FOLR1-overexpressing tumor cells." (PMID 40836974, 2024). "Taken together, anti-FOLR1 CAR T cells induced rapid tumor eradication, CAR T cell proliferation, and short-term persistence." (PMID 38254822, 2024). "The FOLR1-directed CAR T cells rapidly reduced OV-90 wt tumor burden, confirming the results from the previous study." (PMID 38254822, 2024). "Folate receptor near-infrared imaging involves the use of OTL38 (On Target Laboratories, West Lafayette, Indiana, USA), a folate analog conjugated to a cyanine dye, as a biomarker for tumor tissues that overexpress folate receptor alpha." (PMID 39309550, 2024). "FOLR1 expression was detected in the epithelial tumor cells of all patient samples, indicated by co-expression with EPCAM, which is a well-known marker for human epithelial tissues and carcinomas." (PMID 38254822, 2024). "Luveltamab tazevibulin (STRO-002) is an ADC that also specifically targets the folate receptor alpha (FRα) in tumor cells." (PMID 39590153, 2024). "FOLR1-specific CAR candidates designed with IgG4 hinge (candidates C and G) are associated with slower tumor-killing kinetics, reduced proliferation capacities, and persistency compared to the CAR candidates designed with CD8α hinge (candidates A and E)." (PMID 38254822, 2024). "We investigated the in vivo anti-tumor efficacy of four selected anti-FOLR1 CAR T cell candidates A, C, D, and F, respectively." (PMID 38254822, 2024). "OTL38 is a folic acid analog conjugated to an indo-cyanine green-like dye (excitation wavelength of 774 nm and emission wavelength of 794 nm) that works by leveraging the tumor-specific overexpression of folate receptor alpha (FRα)." (PMID 37193364, 2023). "The human folate receptor-alpha (FRα) was chosen as the target for clinical testing of IgE therapy because of its presence on the cell membrane of a range of tumour types, and very limited expression on normal tissues." (PMID 37491373, 2023). "Folate receptor alpha (FRα) is a glycoprotein that is anchored to the cell membrane of normal epithelial cells and highly expressed in a variety of tumor cells of epithelial origin, including lung, colorectal, ovarian, etc.." (PMID 37207165, 2023).
tumor (continued). "Systemic administration of a monospecific FOLR1-targeted prodrug combination led to a significant growth inhibition of established SK-OV-3 tumor xenografts in mice." (PMID 35073465, 2022). "A possible strategy to circumvent on-target off-tumor toxicity is the use of dual targeting/AND-gated CARs requiring binding to both FOLR1 and a hematopoietic cell–specific marker to elicit T cell–mediated killing of tumor cells." (PMID 36136600, 2022). "FOLR1 staining was detected by immunohistochemistry in the renal tubular epithelium and luminal surface of pulmonary epithelium (patchy), raising concerns for on-target/off-tumor toxicity with FOLR1-targeted therapies." (PMID 36136600, 2022). "Another limitation is that the level of FOLR1 is affected by the tumor histotype, clinical grade, stage, and tumor size." (PMID 36233339, 2022). "The folate receptor alpha (FR) is a well-known tumor marker that is overexpressed in 40% of human cancers, and it is rarely expressed or inaccessible in most normal cells." (PMID 35335867, 2022). "Although their analysis revealed that high FOLR1 expression was not limited to TNBC tumors, this type of tumor was significantly associated with increased expression of FOLR1 mRNA compared with ER+ and HER2+ tumors." (PMID 33535554, 2021). "More specifically, the high-affinity FolR1-TCB was approximately 100-fold more potent towards the high expression tumor cell line compared with the low-expression line." (PMID 34862519, 2021). "The T47D tumor cells, which exhibited FOLR1 expression, occurred only in the peripheral area (Figure 6e2–e4)." (PMID 33535554, 2021). "Of note, the humanised mAb-drug conjugate mirvetixumab soravtansine showed promising results in tumours with high FOLR1 expression when assessed in Phase III trials for the treatment of platinum-resistant EOC, but not MOC specifically." (PMID 34830751, 2021). "Contrary to the in vitro condition, FOLR1 expression was observed in MCF7 tumor tissue by IHC analysis, suggesting that FOLR1 expression was induced by certain conditions in the in vivo model that was not provided in vitro." (PMID 33535554, 2021). "As a result of that design, FOLR1(Lo) TCB presented a lower binding to FOLR1-expressing HeLa cells while retaining a potent killing activity in coculture assays and an in vivo tumor control efficacy." (PMID 34378534, 2021). "The expression profile of FOLR1 was investigated in two studies with varied results, but nevertheless, demonstrated elevated expression frequencies in MOC, thus aligning with prior notions of FOLR1 overexpression in tumour cells." (PMID 34830751, 2021). "Tumour specificity was demonstrated using an anti-folate receptor 1 (FOLR1) T-cell bispecific antibody engineered with an anti-idiotypic anti-CD3 ‘mask’ joined to an anti-CD3 Fab region via a protease-cleavable linker." (PMID 33469153, 2021). "Tumor growth and FOLR1 expression were assessed in T47D and MCF7 orthotopic xenograft mouse models after a single intravenous administration of MORAb-202 (5 mg/kg)." (PMID 33535554, 2021). "The cells with FOLR1 expression were mainly found in the tumor tissues from patient 3, but the mechanically dissociated tissue of patient 1 also contained this cell subset." (PMID 33670410, 2021). "For primary human bronchial epithelial cells and primary human renal cortical cells expressing low amounts of FOLR1, the masking significantly reduced target cell killing even at concentrations tenfold higher than the one used for tumor cells." (PMID 32581215, 2020). "In order to demonstrate the reduction of target cell lysis by blocking of the anti-CD3 Fab, the dose-dependent T-cell killing of FOLR1-positive tumor cells by Prot-FOLR1-TCBs was measured after 48 h." (PMID 32581215, 2020). "Unmasking results in efficient killing of FOLR1-positive tumor cells in vitro and in vivo while sparing normal cells with low FOLR1 expression." (PMID 32581215, 2020).